VKORC1 (vitamin K epoxide reductase complex subunit 1)
Diseases named in the same sentence as VKORC1 in open-access papers (continued):
Sharing a sentence is not in itself a finding about the gene and the disease.
tumor (6 papers, 2014 to 2025). "In the model, we constructed a predictive scoring system with high accuracy and screened out key MDMs-related genes associated with prognosis and M2 TAMs, among which VKORC1 may be involved in GC progression and iron death in tumor cells." (PMID 37880233, 2023). "This suggests that VKORC1 could be involved in regulating the proliferation and in the programmed death of tumor cells through vitamin K. However, specific mechanisms are still unclear, especially about TAMs and immune cells." (PMID 37880233, 2023). "We also observed that hub gene VKORC1 might be involved in GC progression and iron death of tumor cells." (PMID 37880233, 2023). "Does over-expression of Ggcx and Vkorc1 contribute to tumorigenicity of the tumor microenvironment?" (PMID 27916840, 2016). "Therefore, we speculate that VKORC1 may play a role in tumor progression and may also be regulated by TAMs." (PMID 37880233, 2023). "ScRNA‐seq data show that vitamin K cycle genes(NQO1, UBIAD1, GGCX, VKORC1, VKORC1L1) are specifically expressed in tumor cells." (PMID 41028931, 2025). "TMX4, ALPL, PTX3, BHLHE40, TNFRSF12A and CST3 demonstrated significant overexpression in LUSC tumour tissues, whereas CLDN1, VKORC1 and ADD3 exhibited significant underexpression in the HPA database." (PMID 38520221, 2024). "Notably, TMX4, ALPL, PTX3, BHLHE40, TNFRSF12A and CST3 demonstrated significant overexpression in LUSC tumour tissues, whereas CLDN1, VKORC1 and ADD3 exhibited significant underexpression." (PMID 38520221, 2024).
renal disease (1 paper, 2025). "The data thus far suggests that genetic variants within the VKORC1 gene affect the risk of vascular calcification in patients with renal disease in several ethnic groups, but to date, their role in arterial stiffness has not been investigated." (PMID 41465069, 2025). "Given that renal disease is polygenic and multifactorial in nature, the effects of the VKORC1 −1639G>A, +2255C>T, and +3730G>A polymorphisms might be less apparent in patients with higher calcification scores." (PMID 41465069, 2025).
VKORC1 also shares sentences with these, for which no sentence is quoted: heart failure (3 papers); hemorrhage (3); Osteopenia (3); Alzheimer’s dementia (2); hypothyroidism (2); myopathy (2); acute coronary syndrome (1); age-related macular degeneration (1); allergic rhinitis (1); antithrombin deficiency (1); Aortic dissection (1); Cognitive impairment (1); congestive heart failure (1); dyslipidemia (1); glioma (1); Glucose intolerance (1); gout (1); heart disease (1); Hepatitis (1); hepatitis B (1); hepatitis C (1); hyperthyroidism (1); hypertriglyceridemia (1); infectious disease (1); intracranial haemorrhage (1); major depressive disorder (1); measles (1); mesothelioma (1); myxedema (1); neuroblastoma (1).
A further 7 diseases each share a sentence with VKORC1 in 1 paper.